MSH4 (mutS homolog 4)
Description:
Involved in meiotic recombination. Required for reciprocal recombination and proper segregation of homologous chromosomes at meiosis.
Synonyms: ASG; POF20; SPGF2
Tractability: No criterion of Open Targets' tractability assessment is met for any kind of drug.
Gene: Protein-coding gene on chromosome 1 (75,796,882 to 75,913,242, forward strand). Ensembl gene ENSG00000057468.
Subcellular location: Chromosome
Subcellular location (Human Protein Atlas): Nucleoplasm; Equatorial segment; Flagellar centriole; Mid piece
Pathways (Reactome):
Reproduction: Meiotic recombination
Gene Ontology:
Molecular function: protein binding; DNA binding; ATP binding; ATP-dependent DNA damage sensor activity; mismatched DNA binding
Biological process: reciprocal meiotic recombination; mismatch repair
Cellular component: DNA repair complex; chromosome; nucleus; condensed chromosome; condensed nuclear chromosome; recombination nodule; synaptonemal complex
Genetic constraint (gnomAD): Loss-of-function variants: 40 observed, 43.74 expected, observed/expected ratio (o/e) 0.91, 90% interval 0.71 to 1.19. The upper end of that interval is the gene's LOEUF score, 1.19, which puts it in group 5 of 6, group 1 being the genes least tolerant of losing a copy. Missense variants: 561 observed, 543.15 expected, observed/expected ratio (o/e) 1.03, 90% interval 0.96 to 1.11. Synonymous variants: 196 observed, 194.76 expected, observed/expected ratio (o/e) 1.01, 90% interval 0.89 to 1.13.
Homologues: Orthologues: chimpanzee MSH4 (99% identical), macaque MSH4 (98% identical), pig MSH4 (91% identical), guinea pig MSH4 (87% identical), mouse Msh4 (86% identical), rat Msh4 (86% identical), rabbit MSH4 (84% identical), tropical clawed frog rabggtb (68% identical), zebrafish msh4 (57% identical), dog MSH4 (37% identical), Caenorhabditis elegans him-14 (27% identical). Paralogues in human: MSH3 (22% identical), MSH6 (19% identical), MSH5 (17% identical).
Diseases named in the same sentence as MSH4 in open-access papers:
MSH4 is named in the same sentence as 30 diseases in open-access papers, as found by Europe PMC text mining. Sharing a sentence is not in itself a finding about the gene and the disease. The quoted sentences say what the papers report.
breast carcinoma (7 papers, 2009 to 2022). "It has been reported that a single nucleotide polymorphism (SNP)–SNP interaction between MSH4 Ala97Thr/MLH3 Leu844Pro increases breast cancer susceptibility." (PMID 36076047, 2022). "We also found evidence for an interaction (MSH4 Ala97Thr/MLH3 Leu844Pro) associated with an increased risk for breast cancer." (PMID 19781088, 2009). "Moreover, combined mutations in MSH4 and MLH3 were associated with increased risk of breast cancer." (PMID 36076047, 2022). "We carried out a hospital-based case-control study in a Caucasian Portuguese population (287 cases and 547 controls) to estimate the susceptibility to non-familial breast cancer associated with some polymorphisms in mismatch repair genes (MSH3, MSH4, MSH6, MLH1, MLH3, PMS1 and MUTYH)." (PMID 19781088, 2009).
Infertility (6 papers, 2013 to 2024). "In this study, we present the case of a young infertile female who carries compound heterozygous MSH4 variants, 2374 A > G (p.Thr792Ala) and c.2222_2225delAAGA (p.Lys741Argfs*2)." (PMID 37620942, 2023). "Further studies are required to identify the pathological role of the missense variant (NM_002440.4: c.G244A: p.G82S) and investigate the contribution of MSH4 variants in infertile men in larger cohorts." (PMID 35090489, 2022). "Deletion of msh4 in mice leads to meiotic arrest at the diplotene stage and increased chromosomal pairing abnormalities, resulting in infertility in both male and female mice." (PMID 37620942, 2023). "Deletion of msh4 in mice leads to meiotic arrest and increased chromosomal pairing abnormalities, resulting in infertility in both male and female mice." (PMID 37620942, 2023). "Up to now, several variants in MSH4 and MSH5 have been reported in infertile men and women." (PMID 35742973, 2022). "Msh4 or Msh5 knockout mice, while able to initiate meiosis normally, are unable to stabilise intermediates in the HR process and ensure proper chromosome pairing, ultimately leading to a reduced number of oocytes and signs of ovarian failure and infertility in mice." (PMID 37430352, 2023). "Despite early discoveries of the sterility phenotype in msh4−/− mice, the association between MSH4 gene variants and human infertility was not established until 2017." (PMID 37620942, 2023). "Despite the fact that sterility phenotype in msh4−/− mice was discovered as early as 2000, the association of MSH4 gene variants with human infertility was not established until 2017." (PMID 37620942, 2023).
Azoospermia (4 papers, 2021 to 2023). Absence of any measurable level of sperm,whereby spermatozoa cannot be observed even after centrifugation of the semen pellet. "msh4 is an important gene involved in meiosis, and mutations in this gene may be associated with female infertility and male non-obstructive azoospermia." (PMID 37254055, 2023).
bladder cancer (2 papers, 2022 to 2023). "The TCGA−BLCA dataset showed that the expression of RBBP8 and MSH4 was significantly lower in bladder cancer cases as compared to normal samples (p < 0.001)." (PMID 36076047, 2022). "Furthermore, GEO13507 dataset showed that RBBP8 and MSH4 were differentially expressed in bladder cancer cases compared normal tissues by 1.82 and 1.88 fold, respectively (p < 0.001)." (PMID 36076047, 2022).
common variable immunodeficiency (2 papers, 2009 to 2010). "Prior studies have shown that missense mutations that impair MSH5 binding to its obligate heterodimerization partner MSH4 associate with immunoglobulin A deficiency (IgAD) and common variable immunodeficiency (CVID)." (PMID 20805886, 2010). "Increased microhomology at the CSR junctions has also been observed in mice deficient in PMS2, MLH1, MSH4 or MSH5 and in IgAD and common variable immunodeficiency (CVID) patients carrying mutations in the MSH5 gene." (PMID 19008195, 2009).
lung carcinoma (2 papers, 2016 to 2020).
Lynch syndrome (2 papers, 2023). An autosomal dominant hereditary neoplastic syndrome characterized by the development of colorectal carcinoma and a high risk of developing endometrial carcinoma, gastric carcinoma, ovarian carcinoma, renal pelvis carcinoma, and small intestinal carcinoma. "Even though MSH4 has not been identified in Lynch syndrome patients, its similar biological function makes it very likely to produce an effect on the genetic susceptibility to cancer." (PMID 36765901, 2023).
sterility (2 papers, 2023 to 2025). "The other top gene associated with late run timing was msh4, a gene associated with sterility due to meiotic failure as well as diminished ovarian reserves." (PMID 41019293, 2025).
amenorrhea (1 paper, 2023). The absence of menses in a woman who has achieved reproductive age. "The other 11 genes were not linked to a specific type of amenorrhea, including mutations in three genes (HFM1, MSH4 and POLG) previously reported in SA and eight genes described in both PA and SA." (PMID 36732629, 2023).
bladder tumors (1 paper, 2022). "We identified that RBBP8 and MSH4 were the most significantly hypermethylated genes in bladder tumors than in normal tissues (p < 0.001 and p = 0.016, respectively)." (PMID 36076047, 2022). "However, the role of aberrant MSH4 expression have not been previously reported in bladder tumors." (PMID 36076047, 2022).
colon cancer (1 paper, 2022).
colorectal cancer (1 paper, 2020). A primary or metastatic malignant neoplasm that affects the colon or rectum.
cyst (1 paper, 2024). A sac-like closed membranous structure that may be empty or contain fluid or amorphous material. "RAD21, SMC3, and MEI2 are linked to bloom-promoting sex, HOP2 and MSH4 to cyst germination, while SPO11, MND1, and DMC1 are common to both cyst-forming and non-encysting sex." (PMID 39367346, 2024).
Fanconi Anaemia (1 paper, 2016). "This analysis identified several novel ATR synthetic lethal partner genes involved in DNA damage/repair including those targeting components of the HR/Fanconi Anaemia pathway (FANCE, SLX4, PALB2), DNA mismatch repair (MSH4, PMS2) and trans-lesion synthesis (RAD18) pathways." (PMID 27958275, 2016).
glioma (1 paper, 2020). A benign or malignant brain and spinal cord tumor that arises from glial cells (astrocytes, oligodendrocytes, ependymal cells). "Further studies with a panel using more IHC markers, such as Atm, Msh4, Msh5, or other proteins which may be altered in hypermutated gliomas, could potentially improve the sensitivity further." (PMID 32051040, 2020).
Premature ovarian insufficiency (1 paper, 2025). Amenorrhea due to loss of ovarian function before the age of 40. "Recent studies identifying factors responsible for primary and premature ovarian insufficiency (POI) have reported either dramatic downregulation or non-functional variants of several DDR pathway members, such as BRCA1, RAD51, ATR, MSH4, MSH5, and FANC genes." (PMID 40148269, 2025).
tumor (11 papers, 2013 to 2024). "Given the cancer‐specific heterogeneity observed in our findings, more work is needed to better determine the relationship between the mutational landscape of a tumor, MSH4, and TMB." (PMID 37162286, 2023). "MSH4 expression was significantly associated with tumor mutational burden in three publicly available data sets." (PMID 37162286, 2023). "The relationship between MSH4 expression and tumor mutational burden was further explored in three independent tumor data sets." (PMID 37162286, 2023). "The most consistent association we found in LS and between MSI‐H and MSS tumor status was MSH4." (PMID 37162286, 2023). "Together, these data reveal a consistent role for differential methylation of MSH4 in MSI‐H tumors across tumor locations." (PMID 37162286, 2023). "Though no finding reached statistical significance (p < 0.05), each trended in a direction to show that individuals with higher than the median expression of MSH4 expression displayed poorer OS after adjustment for factors such as tumor stage and MSI status." (PMID 37162286, 2023). "Further work will be needed to determine if there is any causal relationship between MSH4 and MSI‐H tumor development." (PMID 37162286, 2023). "For MSH4, methylation odds significantly increased with late tumor stage [OR: 6.82, 95% CI 2.42–21.1, p < 0.001] and muscle-invasive disease [OR: 7.25, 95% CI 2.43–25.0, p < 0.001]." (PMID 36076047, 2022). "Significant associations were also observed for MSH3 rs26279, MSH4 rs5745325, NBN rs1805794, and tumor histotype." (PMID 32957448, 2020). "Interestingly, we found for the first time that RBBP8 and MSH4 methylation and their corresponding gene downregulation were significantly associated with progressive UBC which is in parallel with high tumor stage and muscle-invasive disease." (PMID 36076047, 2022). "Patient No. 1 (MSI tumor) harbored a somatic mutation in MSH4 lending support to the hypothesis that this gene may be involved in the pathogenesis of MSI of GC." (PMID 28683819, 2017). "These include alterations in e.g. MSH4, PRDM2, and TP53I3 in the MSI tumor as well as GATA, DOCK5, and IGSF11 in the MSS tumor." (PMID 28683819, 2017). "Besides, we also observed that MSH4, NBN, NEIL2, OGG1 and XRCC2 were downregulated in both HPV-positive tumor cell lines when compared to the HPV-negative one." (PMID 30674977, 2019).
cancer (8 papers, 2013 to 2024). A tumor composed of atypical neoplastic, often pleomorphic cells that invade other tissues. "Next, we were interested in better defining a clinical role for MSH4 gene expression across three TCGA cancer cohorts by examining the relationship between MSH4 gene expression and TMB." (PMID 37162286, 2023). "Given the important role of dMMR in numerous cancers, future studies should aim to determine whether differences in MSH4 expression may be used in combination with other screening‐based approaches to identify and provide supporting individuals in the general population with dMMR." (PMID 37162286, 2023). "They found that urinary glyphosate level was associated with the methylation level of 24 CpG sites in the promoters of genes including some related to cancer, such as SF3B2, MSH4, and ERCC8." (PMID 39200696, 2024). "Given all this, these four DDR genes (EME2, MSH4, MLH3, and SPO11) have been proved to take part in the pathogenesis, progression, and prognosis of cancers." (PMID 36816926, 2023). "We have identified MSH4 as a consistent feature in colon organoids of LS versus healthy subjects and in MSI‐H versus MSS/MSI‐L tumors across different cancers, establishing MSH4 as a novel marker of LS and dMMR." (PMID 37162286, 2023). "As such, the role of MSH4 as a marker of dMMR in these cancers was not considered." (PMID 37162286, 2023). "Most notably, our findings support an important correlation between MSH4 DNA methylation and gene expression occurring in dMMR/MSI‐H across different cancer types and in both hereditary/nonhereditary conditions." (PMID 37162286, 2023).
adenocarcinoma (1 paper, 2020). A common cancer characterized by the presence of malignant glandular cells. "For MSH4 rs3806162, Patients with adenocarcinoma subgroup carrying GG or GT had shorter PFS." (PMID 32742474, 2020).
hematological malignancies (1 paper, 2023). "Three of them harbor clinically relevant variants in genes with a probable role in the development of inherited forms of hematological malignancies (GATA1, MSH4 and PRF1)." (PMID 36765901, 2023).
MSH4 also shares sentences with these, for which no sentence is quoted: myeloma (2 papers); female infertility (1); immune diseases (1); multiple myeloma (1); nasopharyngeal carcinoma (1); neoplasms of the retina (1); nervous system tumors (1); premature ovarian failure (1); skin cancer (1); spermatogenic failure (1).